NME4 (NME/NM23 nucleoside diphosphate kinase 4)
Description:
Mitochondria-specific nucleoside diphosphate kinase that catalyzes the transfer of a gamma-phosphoryl group from ATP to a nucleoside diphosphate via a ping-pong mechanism involving a phosphohistidine intermediate, participating in nucleoside triphosphate homeostasis. In vitro, purine nucleoside triphosphates are much more effective as donors and acceptors than pyrimidine nucleoside triphosphates, and ribonucleosides derivatives are superior to their deoxyribonucleosides counterparts (By similarity). Associates with cardiolipin-containing mitochondrial inner membrane and locally produces ADP in the mitochondrial intermembrane space, which is directly taken up via the ADP/ATP translocase (ANT) into the matrix to stimulate respiratory ATP regeneration. Also directly provides GTP for mitochondrial GTPases, such as the dynamin-related GTPase OPA1. Additionally, catalyzes the anionic phospholipid transfer, namely cardiolipin, from the mitochondrial inner membrane (IM) to the outer membrane (OM) through the formation of contact sites between IM and OM, in a nucleoside diphosphate kinase-independent manner. The switch between the nucleoside diphosphate kinase and the phospholipid transfer activity may depend on the availability and accessibility of cardiolipin and other anionic phospholipids in the IM outer leaflet and OM inner leaflet.
Synonyms: NDPK-D; NDK4; nm23-H4; NM23H4; NDPKD; NDK
Tractability: Small molecule: it has a binding pocket of medium quality. Antibody: UniProt places it where antibodies can reach, with medium confidence.
Target class: Enzyme; Transferase
Gene: Protein-coding gene on chromosome 16 (396,725 to 410,367, forward strand). Ensembl gene ENSG00000103202.
Subcellular location: Mitochondrion intermembrane space; Mitochondrion matrix; Mitochondrion outer membrane
Subcellular location (Human Protein Atlas): Mitochondria
Pathways (Reactome):
Metabolism: Interconversion of nucleotide di- and triphosphates
Gene Ontology:
Molecular function: cardiolipin binding; mitochondrion-mitochondrion outer membrane tether activity; nucleoside diphosphate kinase activity; phosphatidylglycerol transfer activity; phospholipid binding; protein binding; GTPase binding; protein-containing complex binding
Biological process: intermembrane phospholipid transfer; lipid transport; protein hexamerization; nucleoside metabolic process; nucleoside triphosphate biosynthetic process; CTP biosynthetic process; GTP biosynthetic process; nucleobase-containing small molecule metabolic process; UTP biosynthetic process
Cellular component: mitochondrial inner membrane; mitochondrial intermembrane space; mitochondrial matrix; mitochondrial outer membrane; mitochondrion
Genetic constraint (gnomAD): Loss-of-function variants: 18 observed, 16.57 expected, observed/expected ratio (o/e) 1.09, 90% interval 0.75 to 1.6. The upper end of that interval is the gene's LOEUF score, 1.6, which puts it in group 6 of 6, group 1 being the genes least tolerant of losing a copy. Missense variants: 260 observed, 224.16 expected, observed/expected ratio (o/e) 1.16, 90% interval 1.05 to 1.28. Synonymous variants: 111 observed, 86.58 expected, observed/expected ratio (o/e) 1.28, 90% interval 1.1 to 1.5.
Homologues: Orthologues: guinea pig NME4 (84% identical), mouse Nme4 (83% identical), macaque DECR2 (82% identical), pig NME4 (82% identical), rat Nme4 (82% identical), zebrafish nme4 (64% identical), tropical clawed frog nme4 (61% identical), rabbit NME4 (51% identical). Paralogues in human: NME3 (48% identical), NME1 (45% identical), NME2 (44% identical), NME7 (27% identical), NME8 (25% identical), NME6 (24% identical), NME5 (24% identical), NME9 (14% identical).
Diseases named in the same sentence as NME4 in open-access papers:
NME4 is named in the same sentence as 32 diseases in open-access papers, as found by Europe PMC text mining. Sharing a sentence is not in itself a finding about the gene and the disease. The quoted sentences say what the papers report.
oral cancer (4 papers, 2014 to 2021). "Therefore, NEM4 is a potential miR-196 regulatory target.To determine the association of miR-196 and NME4, the expression levels of these molecules were examined in two lines of normal keratinocytes and four oral cancer cell lines." (PMID 25233933, 2014). "In oral cancer, NME4 expression is inhibited by the microRNA miR-196, whose expression is strongly increased in cancer tissue and correlates with lymph node metastasis." (PMID 34674701, 2021). "For instance, miR-196a-5p was significantly over-expressed in the oral cancer tissues and it accelerated the cell migration and invasion of oral cancer cells through the NME4-JNK-TIMP1-MMP axis." (PMID 30621631, 2019). "In addition, miR-196b-5p has been reported to function as an oncogene in laryngeal SCC by targeting SOCS238, and in oral cancer through regulating the NME4-JNK-TIMP1-MMP signaling pathway." (PMID 32963220, 2020). "Thus, miR-196 appear to fine-tune the invasion mechanism in oral cancer by inhibiting NME4, leading to the activation of p-JNK and MMP1/9 and suppression of TIMP1." (PMID 25233933, 2014).
breast carcinoma (2 papers, 2014 to 2021). "Different cohorts of breast cancer revealed that expression of NME4 is negatively associated with mesenchymal, EMT and tumor invasion markers, but positively associated with epithelial markers." (PMID 34674701, 2021).
breast tumors (2 papers, 2021 to 2023). "In breast tumors and several other tumor types, low NME4 expression was associated with a shorter overall survival, i.e. poor prognosis." (PMID 34674701, 2021). "Consistent with the role of NME4 as a metastasis suppressor in human subjects, low expression of NME4 is associated with shorter overall survival (i.e. poor prognosis) in patients with breast tumors or with several other tumor types." (PMID 37353690, 2023). "The METABRIC database (1904 human breast tumors) consistently revealed a positive association of NME4 with epithelial markers CDH1 and KRT18 and a negative association with mesenchymal markers CDH2 and VIM as well as many EMT drivers like ZEB1, ZEB2, SNAI2, TWIST1, and TWIST2." (PMID 34674701, 2021). "Strikingly, NME4 mRNA levels in this cohort were the lowest in the most aggressive human breast tumors with worst prognosis, the so-called triple-negative breast tumors." (PMID 34674701, 2021). "It is consistent with NME4 mRNA levels in human breast tumor cell lines, which are high in hormone receptor-positive cell lines (favorable prognosis), but low in triple-negative cell lines (poor prognosis)." (PMID 34674701, 2021). "We observed significantly more NME4 mRNA in the HR-positive human breast tumor cell lines than in the normal-like cell lines; these levels significantly decreased in the triple-negative human breast tumor cell lines, reaching a similar level to that observed in normal-like cell lines." (PMID 34674701, 2021). "Importantly, NME4 mRNA levels were the lowest in the most aggressive human breast tumors." (PMID 34674701, 2021). "We first determined mRNA levels of NME4 (encoding NDPK-D), CDH1, and KRT18 (encoding the two well-known epithelial markers E-cadherin and cytokeratin 18, respectively), in an important cohort of 526 human breast tumors from patients with well-documented follow-up by using RT-qPCR." (PMID 34674701, 2021).
fatty liver (2 papers, 2023 to 2024). "Hepatic deletion of Nme4 suppresses the progression of hepatic steatosis." (PMID 38177901, 2024). "In this study, we found that NME4 is upregulated in NAFLD and that its expression is positively correlated with liver steatosis." (PMID 38177901, 2024).
esophageal carcinoma (1 paper, 2021). A primary or metastatic malignant neoplasm involving the esophagus. "In six carcinoma types (breast, ovarian, lung, pancreatic, uterine, and esophageal carcinoma), low expression of NME4 was associated with a poor prognosis; this is also the case for tumors other than carcinomas such as pheochromocytoma, paraganglioma, and sarcoma." (PMID 34674701, 2021).
Hypertension (1 paper, 2018). The presence of chronic increased pressure in the systemic arterial system. "We have also identified 8 important genes (NME4, PNPLA7, GGT5, PTGS2, IGF1R, NT5C2, ENTPD1 and PTEN), a few GO categories and biological pathways that may be associated with the military pilot hypertension." (PMID 29996846, 2018). "We have also identified 8 important genes (NME4, PNPLA7, GGT5, PTGS2, IGF1R, NT5C2, ENTPD1 and PTEN), a number of gene ontology categories and biological pathways that may be associated with military pilot hypertension." (PMID 29996846, 2018). "The results from Western blotting showed that NME4 and PNPLA7 these two genes were up-regulated significantly and GGT5, PTGS2, IGF1R, NT5C2, ENTPD1 and PTEN these six genes were down-regulated significantly in PBMCs of military pilots with hypertension." (PMID 29996846, 2018).
liver cancer (1 paper, 2024). An epithelial or non-epithelial malignant neoplasm that arises from the liver. "We also evaluated NME4 expression in human liver cancer cell lines." (PMID 38177901, 2024).
lung adenocarcinoma (1 paper, 2022). A carcinoma that arises from the lung and is characterized by the presence of malignant glandular epithelial cells. "Our study also revealed that high expression of NME4 and POLR3G may adversely affect the poor prognosis of lung adenocarcinoma." (PMID 34996932, 2022).
lung carcinoma (1 paper, 2022). "Four of the five genes (HEG1, PLSCR4, GMFG, and NME4) associated with LC-BC alignments have been observed to be deregulated in lung cancer." (PMID 36101460, 2022).
myopia (1 paper, 2023). "Based on the gene expression patterns of those pathways, G6pd2 and Rpia in NADPH synthesis and Nme4 and Xbp1 in integrator stress response might be potential candidate genes of oxidative stress on myopia." (PMID 38136985, 2023).
non-small cell lung carcinoma (1 paper, 2021). A group of at least three distinct histological types of lung cancer, including non-small cell squamous cell carcinoma, adenocarcinoma, and large cell carcinoma. "This is also the case for non-small cell lung cancer, where NME4 silencing was shown to inhibit proliferation." (PMID 34674701, 2021).
Sepsis (1 paper, 2025). Sepsis is defined as life-threatening organ dysfunction caused by a dysregulated host response to infection. "Both ZAP70 and NME4 showed the strongest binding affinity for lumichrome, highlighting the potential relevance of this metabolite in sepsis-induced immunosuppression." (PMID 40761792, 2025).
squamous cell carcinoma (1 paper, 2026). A carcinoma arising from squamous epithelial cells. "Additionally, NME4 modulated the immune microenvironment through the NFκB2–CCL5 axis, which restricts CD8+ T cell tumor infiltration in squamous cell carcinoma." (PMID 41584726, 2026).
steatosis (1 paper, 2024). Increased lipid within the cytoplasm of cells. "Nme4 is markedly upregulated in mice fed with high-fat diet, and its expression is positively correlated with the level of steatosis." (PMID 38177901, 2024). "NME4 promotes de novo lipogenesis potentially through the direct binding and activation of key enzymes involved in CoA metabolism, ultimately leading to lipogenesis and steatosis in NAFLD." (PMID 38177901, 2024).
cancer (10 papers, 2014 to 2026). A tumor composed of atypical neoplastic, often pleomorphic cells that invade other tissues. "In human cancer, NME4 expression is negatively associated with markers of epithelial-mesenchymal transition and tumor aggressiveness and a good prognosis factor for beneficial clinical outcome." (PMID 34674701, 2021). "Taken together, these data show that positive association of NME4 expression with beneficial clinical outcome is a generic trait in cancer." (PMID 34674701, 2021). "In human cancer, NME4 expression correlates negatively with markers of EMT and tumor aggressiveness." (PMID 37353690, 2023). "Low levels of NME4 expression also correlated with high levels of metastasis in various types of cancer in humans." (PMID 37353690, 2023). "We applied a hard filter to the GSMs and finally selected six genes (CLDN3, DECR2, EVA1B, NME4, NTSR1 and XPNPEP3) associated with epigenetic regulation, differentiation and cancer (Pearson’s correlation test; p-value ≤ 0.001)." (PMID 31040866, 2019). "miR-196 is over-expressed in the cancer tissues and is correlated with lymph node metastasis, promoteing cancer cell migration and invasion through NME4-JNK-TIMP1-MMP signaling." (PMID 28968979, 2017). "By contrast, NME4 expression was reduced in all cancer cell lines at both mRNA (3.9 fold) and protein levels (2.3 fold)." (PMID 25233933, 2014). "In addition, NME4 regulates PD‐L1 expression through the STAT3 signaling pathway, which is associated with immune evasion in aggressive cancers." (PMID 41584726, 2026). "Since there are no reports of NME4 associated with the development of any cancer, it might be a novel prognostic signature in LUAD." (PMID 34393804, 2021). "To date, only few studies addressed NME4 expression in human cancers as compared to the non-tumoral tissue." (PMID 34674701, 2021).
tumor (8 papers, 2017 to 2026). "NME4, another gene identified in this study, has been implicated in mitochondrial function and tumor metastasis." (PMID 41584726, 2026). "With anti-programmed cell death protein-1 therapy, inhibition of the immunological rejection-associated neo-oncogene NME4 in LUAD enhanced CD8+ T cell activity and abundance and supported in vivo anti-tumor immunity." (PMID 40894221, 2025). "GTP fueling to mitochondrial dynamin-related OPA1 (by mitochondrial NME4) promotes mitochondrial inner membrane fusion, a process inhibitory to migration and invasion of tumor cells." (PMID 37353690, 2023). "In several cohorts of breast cancer patients, expression of NME4 is negatively associated with markers of mesenchymal cells, the EMT, and tumor invasion, but is positively associated with epithelial markers." (PMID 37353690, 2023). "The outcome was then compared between low and high NME4 expression groups in eight different tumor types." (PMID 34674701, 2021). "Taken together, our data and those of available literature indicate that NME4 expression would increase during formation of the primary tumor and then would decrease when the tumor becomes metastatic." (PMID 34674701, 2021). "NME4 regulates CD8+ T cell infiltration into the tumor microenvironment." (PMID 40761792, 2025). "We further observed an overall negative association between NME4 and tumor invasion markers like genes encoding matrix-degrading proteases (MMP7, ADAM17) and actin cytoskeleton remodelers (ROCK1, ROCK2, LIMK2, CFL2, MYO5A)." (PMID 34674701, 2021). "By integrating multiomics data, we identified TK1, NME4, and RRM2B as key biomarkers that influence tumor progression, immune modulation, and treatment response." (PMID 41584726, 2026). "A tumour metastasis PCR array showed that the expressions of many genes (ECADHERIN, NME4, SYK, CD44 and IL1B) were changed in NPC cells with HOPX overexpression." (PMID 28146149, 2017). "Compelling evidence shows that S10A4 is directly involved in the formation of metastases without affecting the initiation and growth of the primary tumor, hence appearing as a pro-metastatic protein, unlike NDPK-A/NME1 and NDPK-D/NME4 that are metastasis suppressors." (PMID 34674701, 2021).
NME4 also shares sentences with these, for which no sentence is quoted: cervical carcinoma (2 papers); breast adenocarcinoma (1); breast invasive carcinoma (1); cervical adenocarcinoma (1); co-infection (1); essential thrombocythemia (1); glioblastoma (1); insomnia (1); invasive carcinoma (1); metabolic disease (1); neuroblastoma (1); nonalcoholic fatty liver disease (1); ovarian carcinoma (1); paraganglioma (1); pheochromocytoma (1); sarcoma (1).